TLR9 (toll like receptor 9)
Diseases named in the same sentence as TLR9 in open-access papers (continued):
Sharing a sentence is not in itself a finding about the gene and the disease.
prostate carcinoma (continued). "However, the role of TLR9 in the pathophysiology of prostate cancer is unclear." (PMID 23761830, 2013). "In prostate cancer, activation of TLR2, TLR4, and TLR9 stimulates tumor growth while activation of TLR3, TLR4, TLR5, and TLR7 suppress tumor development." (PMID 41601666, 2026). "TLR9-MMP signaling regulates invasion in a variety of cancer cells, including breast and prostate cancers, and the TLR-9-mediated invasion of oral cancer cells is promoted via activation of the DNA-binding activity of at least in part AP-1 TLR-9 signaling." (PMID 36611945, 2022). "It has been reported that nobiletin inhibits the growth of prostate cancer cells by suppressing TLR4/TRIF/IRF3, TLR9/IRF7 and AKT signaling pathways." (PMID 34548474, 2021). "For example, intratumoral administration of SD-101, a TLR-9 agonist, with or without Pembrolizumab in oligometastatic prostate cancer patients undergoing radiotherapy is under phase-II investigation." (PMID 40260236, 2025). "Prostate cancer cells that express low or no TLR9 fail to undergo an invasive phenotype upon CPG-ODN treatment, emphasizing TLR9-specific signaling within the tumor cell as an important driver for enhancing cancer progression." (PMID 38201300, 2024). "Rather than becoming immunogenic, TLR9+ prostate cancers are reportedly less differentiated, more aggressive and prone to reoccur." (PMID 26046794, 2015). "Finally, we demonstrated the feasibility of using TLR9-targeted siRNA delivery to block RELA- and STAT3-dependent prostate cancer cell self-renewal in vivo." (PMID 26046794, 2015). "Despite the mechanism of TLR9 promoting prostate cancer has not been totally understood, substantial evidence suggest that stimulation of TLR9 by synthetic DNA ligands or bacterial DNA results in increased capability of cancer cell invasion." (PMID 26087186, 2015). "Genome-wide transcriptional analysis of prostate cancer cells isolated from xenotransplanted TLR9-positive and -negative tumors revealed a unique gene expression signature, with prominent upregulation of inflammation- and stem cell-related markers." (PMID 26046794, 2015). "Depending on culture conditions, both LN-TLR9HI and PC-TLR9HI cells differentiated into adipocyte- or osteoblast-like cells while prostate cancer cells with low levels of TLR9 failed to differentiate." (PMID 26046794, 2015). "Rather than becoming immunogenic, TLR9+ prostate cancers were less differentiated, more aggressive and prone to reoccur." (PMID 26046794, 2015). "Prostate cancer-specific progression-free survival was significantly longer for patients whose tumors were graded as negative for cytoplasmic TLR9 expression, as compared with patients whose tumors were strongly immunopositive for cytoplasmic TLR9 (P=0.009)." (PMID 23761830, 2013). "The mean prostate cancer-specific progression-free survival times for TLR9-negative and TLR9-positive tumors were 147 (95% CI, 138–161) and 116 (95% CI, 105–128) months, respectively (P=0.009)." (PMID 23761830, 2013). "TLR9 staining was also detected in prostate cancer stroma, however there are no published results with regard to the prognostic role of TLR9 staining in prostate cancer stroma." (PMID 23761830, 2013). "Thus, TLR9/LIF/STAT3 signaling-targeting oligonucleotide-based inhibitors (e.g., CpG-STAT3dODN) may present novel prospects for prostate cancer immunotherapy." (PMID 40727443, 2025). "However, the function and mechanism of Toll-like receptor-9 (TLR9) in prostate cancer is not totally understood." (PMID 26087186, 2015). "We found that positive lymph node metastasis (HR:10.54, 95% CI:2.94–37.80, P < 0.001) and preoperative PSA (HR:1.27, 95% CI:1.11–1.46, P = 0.001) were independent factors of poor prognosis in prostate cancer, while high TLR9 expression were not an independent factor for predicting prognosis." (PMID 26087186, 2015).
prostate carcinoma (continued). "This suggests that TLR9 activation in immune cells could also be favorable in prostate cancer, although the evidence for this remains experimentally unclear probably due to a lack of prostate cancer models that employ orthotopic tumor implantation." (PMID 38201300, 2024). "We verified that in the absence of any transfection reagents in vitro, TLR9-positive PC3-luc and DU145 prostate cancer cells, efficiently internalize CpG-siRNA." (PMID 26046794, 2015).
lupus nephritis (32 papers, 2008 to 2026). Glomerulonephritis in the context of systemic lupus erythematosus. "Another study showed that the significant genotypic and allelic association between rs352140 and lupus nephritis was accompanied by a higher level of TLR9 transcripts in biopsies of lupus nephritis patients." (PMID 37139337, 2023). "TLR9 is absent in mesangial cells of MRL/lpr mice but other groups found TLR9 in tubular epithelial cells of NZBxNZW mice and in diagnostic biopsies of patients with lupus nephritis." (PMID 29650017, 2018). "The potential pathogenic implication of this finding is underlined by the observation that podocyte expression of TLR9 in lupus nephritis associates with the intensity of proteinuria and the progression to CKD45." (PMID 28600543, 2017). "Previously, TLR9 has been associated with renal disease, such as glomerulonephritis and lupus nephritis." (PMID 21929816, 2011). "B cell–specific TLR7 drives severe lupus nephritis in TLR9-deficient MRL/lpr mice." (PMID 37606042, 2023). "In addition, relationships between two other TLR9 gene polymorphisms (rs352139, rs352140) and lupus nephritis development in a Chinese Han population were observed." (PMID 28677621, 2017). "TLR3, TLR7, and TLR9 were reported in the kidneys of patients with lupus nephritis (LN) in correlation with the clinic-pathological indices." (PMID 39000140, 2024). "In comparison, TLR-9 was overexpressed in the tubulointerstitial compartment in patients with lupus nephritis, and TLR-9 depletion exacerbated autoimmune kidney diseases." (PMID 33644078, 2021). "To assess the role of TLR9 in lupus nephritis, we administered our inhibitory anti-TLR9 mAb to NZBWF1 mice." (PMID 34868046, 2021). "In fact, inhibition of TLR9 signaling with synthetic ODN can also exhibit beneficial effects on the progression of lupus nephritis in MRLlpr/lpr mice." (PMID 33168076, 2020). "In patients with lupus nephritis, polyoma virus infection, or hemolytic uremic syndrome, TLR9 was found to be de novo expressed in podocytes and thought to be involved in immune response and inflammation in glomeruli." (PMID 28228761, 2017). "Other research demonstrates greater TLR9 expression in the glomeruli of patients with lupus nephritis, and that the stimulation of glomeruli with endogenous TLR9 ligands augments inflammatory reactions in the kidneys." (PMID 24692849, 2014). "TLR-9 has been shown to be involved in antigen-induced immune complex glomerulonephritis and lupus nephritis through regulation of both humoral and cellular immune responses." (PMID 23472199, 2013). "Recent studies have suggested roles for TLR-9 in the development of renal diseases such as glomerulonephritis and lupus nephritis." (PMID 23472199, 2013). "Furthermore, research has demonstrated a significant correlation between rs352140 and lupus nephritis, as well as elevated levels of TLR9 transcripts." (PMID 40821978, 2025). "Accordingly, in the MRL/lpr mice, TLR9-deficiency in B cells, but not in other major immune cell types, is sufficient to exacerbate lupus nephritis." (PMID 36389822, 2022). "The results showed that both of the nanoflowers, as specific antagonists for TLR7 and TLR9, could decrease the level of autoantibodies, reduce cytokine secretion, and alleviate lupus nephritis in mice." (PMID 36555668, 2022). "In contrast, blockade of TLR7, TLR9, or both attenuates lupus nephritis." (PMID 34760904, 2021). "In the normal kidney, TLR9 expression has been detected in the renal tubules and interstitial tissue, while the tubulointerstitial and glomerular expression has been detected in lupus nephritis." (PMID 21929816, 2011). "The purpose of this study was to compare the plasma expression of TLR7 and TLR9 in HC and in recently diagnosed Class III and Class IV lupus nephritis (LN) patients with 12-month follow-up." (PMID 39000140, 2024).
lupus nephritis (continued). "TLR9 mRNA expression is also upregulated in PBMCs from SLE patients, correlates with lupus nephritis, and correlates with circulating anti-DNA autoantibody levels." (PMID 29650017, 2018). "The TLR7 blocker of the IRS 661 nanoflower and the TLR9 antagonist of the IRS 869 nanoflower could decrease autoantibodies, reduce cytokine secretion, and alleviate lupus nephritis in mice." (PMID 36555668, 2022). "In childhood-onset lupus nephritis injured podocytes stained positive for TLR9, while TLR9 was absent in podocytes of healthy control kidneys or during remission of lupus nephritis." (PMID 29650017, 2018). "In the light of the promising data demonstrating the efficacy of a dual TLR7/TLR9 antagonist and suggesting an “anti-TLR7/9” effect of antimalarials, the results of this study further support the role of TLRs as potential target of lupus nephritis." (PMID 27635115, 2016). "The expression of TLR-9 in resident renal cells is arguable since some researchers have shown TLR-9 to localize solely on infiltrating cells, whilst other researchers have observed increased TLR-9 expression in tubular epithelial cells and glomerular cells during active lupus nephritis." (PMID 22761629, 2012). "Indeed, under TLR9 activation in vivo, anti-DNA Carabin−/− B cells were producing autoantibodies, leading to the development of a disease similar to mesangial type II lupus glomerulonephritis (ISN/RPS classification of lupus nephritis) with a incomplete prevalence." (PMID 23109291, 2012). "However, the IRS 954 nanoflower, the TLR7 and TLR9 dual antagonist, did not have additive or opposing effects on lupus nephritis but only showed a decrease in serum IFNα, suggesting that the TLR7 and TLR9 antagonist may have a competition mechanism or signal-dependent switching relationship." (PMID 36555668, 2022).
lymphoma (32 papers, 2013 to 2025). A malignant (clonal) proliferation of B- lymphocytes or T- lymphocytes which involves the lymph nodes, bone marrow and/or extranodal sites. "Gain-of-function CD79 and MyD88 mutations hyperactivate BCR/TLR9 signaling in several types of lymphoma, including the diffuse large B cell lymphoma (DLBCL) MyD88/CD79B-mutated (MCD) subtype." (PMID 40924473, 2025). "Signaling through TLR9 stimulation by exogenous or endogenous ligands plays a fundamental role in host immune-response and subsequently lymphoma risk." (PMID 35905120, 2022). "Fewer studies have investigated the associated risk of TLR9 polymorphism on lymphoma development in the Arab region." (PMID 35905120, 2022). "The exact contribution of indirect versus direct antitumor effects will be explored in our further studies in TLR9-deficient lymphoma models." (PMID 29433938, 2018). "Recently, it was shown that frequent lymphoma-associated mutations of MYD88 (myeloid differentiation primary response 88) adaptor protein lead to its spontaneous association with Toll-like receptor 9 (TLR9) and BCR, forming a My-T-BCR complex capable to trigger NF-κB activation." (PMID 38203179, 2023). "In lymphoma, a recent study reported a positive correlation between high expression of TLR9 and PD-L1 with poor prognosis in angioimmunoblastic T-cell lymphoma (AITL)." (PMID 40437466, 2025). "A BCAT1 antagonist diminished outgrowth of BCR/TLR9-driven lymphomas in vivo, including a patient-derived xenograft (PDX)." (PMID 40924473, 2025). "In DLBCL, neutrophils are reported to form extracellular traps, then up-regulate the Toll-like receptor 9 pathway and subsequently promote the lymphoma progression." (PMID 40589747, 2025). "A BCAT1 antagonist diminished outgrowth of BCR/TLR9-driven lymphomas in vivo, including a patient derived xenograft." (PMID 38854072, 2024). "Tumor progression was promoted by the activation of Toll-like receptor 9 (TLR9), which is in a downstream pathway activated by lymphoma-derived IL-8." (PMID 36059520, 2022). "A particular single nucleotide polymorphism (SNP) on Toll-Like Receptor 9 (TLR9) has been the center of multiple studies that analyzed its relation to lymphoma formation; this SNP is rs5743836 (TLR9-1237T>C)." (PMID 35905120, 2022). "A phase I trial combining E with external beam radiation therapy (XRT) and investigational TLR9 agonist SD-101 in patients with lymphoma is based on the synergistic effect of XRT and CPI." (PMID 30338242, 2018). "The STAT3 inhibition, through the reversible decoy effect, combined with concurrent TLR9 activation seemed sufficient for the induction of the lymphoma differentiation to antigen-presenting phenotype, thereby ensuring therapeutic antitumor efficacy." (PMID 29433938, 2018). "In the TLR9 IHC expression analysis, only lymphoma cells were considered." (PMID 40437466, 2025). "This analysis suggests that METTL3, YTHDF1, and TLR9 may have influence on lymphoma development and prognosis, via modulating immune microenvironments." (PMID 38537697, 2024). "The clinical application of intralesional administration of the SD101 TLR9 agonist has proven efficacy in untreated indolent lymphomas, in combination with local radiotherapy, achieving in some patients a reduction in tumor size not only of the treated lesion but also in their untreated sites." (PMID 37365634, 2023). "Recent studies demonstrated that SNAs with liposomal cores that carry CpG oligonucleotides activate TLR9 more potently when compared to linear oligonucleotides and show remarkable activity against murine lymphoma due to multivalent, high-affinity binding to TLR9." (PMID 35406387, 2022). "These factors can inhibit the effect of this TLR9 agonist on lymphoma B-cells." (PMID 23561041, 2013). "TLR9 expression may influence the tumor immunophenotype and thus has potential to improve chemotherapy and is currently in clinical trials for other types of cancers (eg. lymphomas, colorectal cancer)." (PMID 29190881, 2017).
lymphoma (continued). "In clinical lymphoma samples, the expression of METTL3, YTHDF1, and TLR9 was highly correlated with immune cells infiltration." (PMID 38537697, 2024). "In experiments using mouse lymphoma cell lines (H11, A20, and BL3750), ibrutinib enhanced the anti-tumor immune response induced by intratumoral injection of a toll like receptor 9 (TLR9) ligand, and promoted T cell-dependent tumor regression." (PMID 37153795, 2023). "Here, we compare the immunomodulatory effects of T-HIFU and M-HIFU ablation with or without the TLR9 agonist CpG in the ovalbumin-expressing lymphoma model EG7." (PMID 36569907, 2022). "We used BJAB cells, an EBV-negative Burkitt-like lymphoma cell line, which is uniquely sensitive to stimulation by CpG and non-CpG oligonucleotides in a sequence and TLR9 dependent fashion." (PMID 34417625, 2021). "For example, the anti-lymphoma effect of PG545 in vivo seems to require NK (natural killer) cell activation and this activation involves PG545 acting via TLR9 (toll-like receptor-9) to trigger dendritic cells to release IL-12, which is necessary for PG545 activation of NK cells." (PMID 28974047, 2017). "BCAT1 inhibition blunted BCR/TLR9, but not CD40L/IL4-triggered B-cell proliferation, IL10 expression and BCR/TLR pathway-driven lymphoma xenograft outgrowth." (PMID 38854072, 2024). "Another previous study demonstrated the formation of a multiprotein supercomplex composed of MYD88, TLR9, and the BCR (My-T-BCR) as a mode of oncogenic BCR signaling in various lymphomas, yet this was not evident in CLL LN biopsies." (PMID 37100883, 2023). "In a lymphoma mouse model, a TLR9 agonist (intratumoral CpG) in combination with anti-OX40 and anti-CTLA-4 cured large and systemic lymphoma tumors without the need for chemotherapy." (PMID 30853982, 2019).
gastric cancer (31 papers, 2012 to 2025). A primary or metastatic malignant neoplasm involving the stomach. "The findings suggested that TLR9 (-1237 T/C and − 1486 T/C) have some roles in the associated risk of gastric cancer." (PMID 37875868, 2023). "In this meta-analysis, we evaluated the influence of two prominent SNPs (1237 C/T and − 1486 T/C) in the TLR9 gene on the risk of gastric cancer across six countries." (PMID 37875868, 2023). "TLR9 has been associated with tumorigenesis at late stage of gastric cancer but it appears to play a minimal role in cytokines secretion as shown in an infected knockout mouse model." (PMID 36317079, 2022). "Recent studies have determined the association of TLR9 polymorphisms with human susceptibility to gastric carcinoma and its prognosis in Chinese population." (PMID 28061847, 2017). "We investigated the association between the TLR9 -1486T/C polymorphism and H. pylori infection risk in gastric cancer patients as well as in the control group." (PMID 23776537, 2013). "In the stratification analysis, we found that the TLR9 -1486T/C polymorphism was associated with an increased risk of gastric cancer among subgroups of younger subjects (age <60 years old) but not older subjects." (PMID 23776537, 2013). "In the present study, we found that the TLR9 -1486T/C polymorphism is associated with an increased risk of gastric cancer in the Chinese population." (PMID 23776537, 2013). "Kaplan–Meier survival curves showed that overall survival of gastric cancer patients was associated with the TLR9 -1486 genotypes." (PMID 23776537, 2013). "Our results suggest that TLR9 -1486C carriers are associated with an increased risk and poor prognosis of gastric carcinoma in the Chinese population." (PMID 23776537, 2013). "Recently, the circulating levels of soluble forms of TLR2, TLR4, and TLR9 were positively associated with advanced stages of gastric cancer, including an upregulation of the protein levels on circulating immune cells in patients with gastric cancer compared to those with premalignant lesions." (PMID 40362298, 2025). "In addition, the TLR9 rs5743836 and rs187084 polymorphisms were linked to a significant oncogenic risk of gastric cancer." (PMID 38685971, 2024). "Several polymorphisms in the TLR9 gene, including functional polymorphism −1486 C/T (rs187084), situated in the promoter of the TLR9 gene in 3p21.3 locus, have been associated with cervical and endometrial cancer, as well as gastric cancer." (PMID 38850110, 2024). "The findings suggested that TLR9 (-1486 T/C) may play a role in the risk of gastric cancer specific to the Asian ethnic group." (PMID 37875868, 2023). "Thus, a study performed on 168 healthy Caucasian from the West of Scotland, first-degree relatives of gastric cancer patients, showed a significant association between a functional polymorphism TLR9-1237T>C and H. pylori-related premalignant gastric lesions." (PMID 30863783, 2019). "In addition, we found that a high expression of TLR1, TLR2, TLR4, TLR5, TLR7, and TLR9 associated with an intestinal-type gastric cancer and with a high expression of all other TLRs." (PMID 31467388, 2019). "Therefore, in this study, we aimed to explore the tissue expression of TLR1, TLR2, TLR4, TLR5, TLR7, and TLR9 as potential prognostic biomarkers in gastric cancer patients, and to examine their associations with several clinicopathological variables." (PMID 31467388, 2019). "Stratified analyses between TLR9 -1486 T/C polymorphisms and gastric cancer risk." (PMID 23776537, 2013). "We evaluated the role of the TLR9 -1486T/C polymorphism in gastric cancer in different age groups." (PMID 23776537, 2013). "TLR9 expression and signaling is quite important in H. pylori-associated gastric cancer." (PMID 23776537, 2013). "The aim of this study was to determine whether the polymorphisms of TLR4 and TLR9 are associated with susceptibility to gastric carcinoma and its prognosis." (PMID 23776537, 2013).